STAT3 (signal transducer and activator of transcription 3)
Diseases named in the same sentence as STAT3 in open-access papers (continued):
Sharing a sentence is not in itself a finding about the gene and the disease.
cancer (continued). "BBI608, an oral cancer stemness inhibitor that blocks STAT3-mediated transcription of cancer stemness genes in the β-catenin pathway, has reached Phase II and III to treat metastatic colorectal cancer." (PMID 33322216, 2020). "Systematic proteomic investigation of secreted disease mediators identified the leukemia inhibitory factor (LIF) as a key paracrine factor from CAFs for STAT3 activation in cancer cells of the epithelial compartment." (PMID 32752017, 2020). "Here, we mainly review the role of STAT3 in mediating radioresistance from points of apoptosis, aggressive behaviors, DNA damage repair, cancer stem cells." (PMID 32733808, 2020). "Signal transducers and activator of transcription 3 (STAT3) is a signaling pathway involved in the progression and malignancy of cancer cells." (PMID 32163546, 2020). "Despite lacking a mitochondrial localization signal, acetylated, serine and tyrosine phosphorylated STAT3 have been detected in mitochondria mostly of cancer cells." (PMID 32331320, 2020). "STAT3 is a transcription factor that is activated in many cancer types and can regulate pathways involving cell proliferation, cell survival, angiogenesis, and tumorigenesis." (PMID 31935877, 2020). "Signal transducer and activator of transcription 3 (STAT3) was shown to play an important role in the development of cancer cell resistance to therapies." (PMID 33327495, 2020). "Aberrant STAT3 pathway activation has been observed in many types of cancer and also functions as an oncogene in promoting cell proliferation, metastasis, epithelial–mesenchymal transition (EMT) and stemness, and chemotherapy resistance." (PMID 32457835, 2020). "Along with its essential role in the progression of cancer, the IL-6/JAK/STAT3 signaling axis incorporates various unexpected components and miRNAs that contribute to JAK/STAT3 activation in cancer." (PMID 31952344, 2020). "Phosphorylation of STAT3 in the tyrosine 705 domain has been found to promote epithelial-mesenchymal transition and metastasis in cancer cells." (PMID 33536913, 2020). "STAT3, an important cancer-promoting transcription factor, was identified to activate SNHG17 transcription in OC." (PMID 32911343, 2020). "A different study reported that the activation of p-STAT3 enhanced cell proliferation, metastasis, and angiogenesis in multiple cancers including NSCLC." (PMID 33173620, 2020). "For instance, IL-32α and IL-32θ inhibit TGFβ-induced EMT, metastasis, and self-renewal in various cancer cells by inhibition of STAT3 activation." (PMID 31952344, 2020). "Among cellular proteins, particular emphasis should be put on the signal transducer and activator of transcription 3 (STAT3), which drives cancer progression and is also crucial in muscle cachexia." (PMID 33158194, 2020). "Several studies have shown STAT3 involvement in the development of resistance for chemotherapy in various cancers." (PMID 32046095, 2020). "This cancer progression effect of STAT3 has been recognized in glioma cells in response to S100B/RAGE." (PMID 32443845, 2020). "It is of interest to note that several shikonin derivatives that target STAT3 have been identified, and some of them were proved to exert anti-cancer activities." (PMID 32536866, 2020). "Several ongoing clinical trials are using different approaches for STAT3 inhibition in cancer patients." (PMID 33330068, 2020). "Several lines of evidence show that the activation of STAT3 is instantaneous in normal cells; however, STAT3 phosphorylation is constitutively accelerated in cancer cells." (PMID 32285621, 2020). "Activation of an inflammatory NF-kB/IL6/STAT3 signaling pathway generates cancer stem cells in breast cancer cells in vitro and is also implicated in colon and other cancers." (PMID 32399610, 2020).
cancer (continued). "Conversely, elevated STAT3 levels in cancer contribute to chemoresistance, thus suggesting that its inhibition can represent an interesting strategy for increasing cancer chemotherapy sensitivity." (PMID 32252311, 2020). "In line with the integration of JAK/STAT and G protein pathways upon chemokine exposure, total STAT3 and phosphoSTAT3 (Y705) levels were enhanced in cancer cells exposed to FAK-depleted CAF CM52." (PMID 32157087, 2020). "Together, these findings provide convincing evidence that STAT3 is activated by radiation and contributes to the cancer phenotype." (PMID 32872659, 2020). "It seems that STAT3 accumulation in cancer cells and its nuclear translocation can lead to radio resistance." (PMID 32545648, 2020). "STAT3 has been shown to be activated in response to chemotherapeutic agents and mediating drug-resistance in several cancers." (PMID 32046095, 2020). "Constitutively elevated phosphorylation of STAT3 at the Tyr705 residue has been frequently observed in many different types of cancer cells and biopsies from cancer patients and is considered as an essential event for its transcriptional activity." (PMID 32973302, 2020). "Particularly, STAT3 is highly activated in various cancers, and activated STAT3 promotes cancer progression." (PMID 32963220, 2020). "And, IL-6 increases angiogenesis by transcriptional upregulation of VEGF in JAK/STAT3 and hypoxia inducible factor 1α (HIF1α) dependent manner in cancer cells." (PMID 33351844, 2020). "Previous studies have shown that IL-6 enhances resistance of a variety of cancers to cisplatin (DDP) treatment via activating STAT3 pathway 29-35." (PMID 32127934, 2020). "First, the maximum sample size of cancer patients was 12 and normal was 3 in the HPA dataset, which made the protein expression of STAT3 in cancer less objective." (PMID 32486001, 2020). "The excessive STAT3 activation in cancer cells is closely connected to the surrounding cancer microenvironment, as well." (PMID 32722030, 2020). "OPB-51602 can directly interfere with mitochondrial STAT3 and induce the formation of STAT3 proteotoxic aggregates that are lethal to cancer cells." (PMID 32872659, 2020). "Growing evidence points to the aberrant activity of STAT3 in cancer providing a potential therapeutic option." (PMID 32486001, 2020). "It is widely accepted that numerous cytokines, GFs, and other oncogenes can activate STAT3 canonically, and thus constitutive activity of STAT3 is observed in high ratio of cancer." (PMID 32722030, 2020). "STAT3 is an oncogenic protein that is overactivated in many types of malignancies, including cancers of blood cells, lung, liver, breast, kidney, ovary, and colon." (PMID 32967366, 2020). "Recent studies demonstrated that STAT3 signaling is involved in the proliferation, apoptosis, and metastasis of cancer cells." (PMID 33114727, 2020). "Reduces STAT3, decrease Slug expression and suppresses cell invasion; inhibits cancer stem cell properties and enhances radiotherapy." (PMID 32872659, 2020). "Certain pro-inflammatory environmental and lifestyle factors promote cancer through nuclear factor-κB (NF-κB) and STAT3 signaling pathways." (PMID 32751207, 2020). "STAT3 is considered as an important oncogene and as an effective therapeutic target for cancer treatment." (PMID 32722030, 2020). "Additional studies demonstrated the efficacy of this STAT3 decoy oligonucleotide in several cancer types, and also illustrated a benefit in overcoming EGFR inhibitor resistance." (PMID 32899142, 2020). "Aberrant STAT3 signaling promotes the initiation and progression of human cancers by either inhibiting apoptosis or inducing cell proliferation, angiogenesis, invasion, and metastasis." (PMID 33040485, 2020).
cancer (continued). "Taken together, these findings indicate that the promotion of metastasis, stem cell-like phenotype, and chemoresistance involves intracellular cooperation between CD44 and STAT3 on a molecular level across numerous cancer models, including ovarian." (PMID 33335857, 2020). "STAT3 has been reported to directly regulate TERT expression in several types of human cancer cells by binding to the promoter region of TERT30." (PMID 32257389, 2020). "The IL-6/JAK2/STAT3/MMP-9 pathway has been described in a variety of human cancers and plays an essential role in microvessel proliferation and BM degradation." (PMID 32047820, 2020). "Activated STAT3, in turn, regulates transcription pathways, which suppress apoptosis and promote the survival of cancer cells." (PMID 32722030, 2020). "In previous section, we mentioned that miRs can function as upstream regulators of the STAT3 signaling pathway in cancer cells." (PMID 32545648, 2020). "Some researchers believe that CA also reduces cancer cell viability through the inactivation of STAT3 signaling and AKT/mTOR pathway." (PMID 32352029, 2020). "Despite the growing number of studies on PHBs and STAT3 in mitochondrial function, their role is poorly understood in cancer biology." (PMID 33257655, 2020). "Since the discovery of the relationship between the constitutive activation of signal transducer and activator of transcription 3 (STAT3) and malignant tumors, the validation of STAT3 as a target has been supported by a large number of studies." (PMID 32752073, 2020). "Some observations suggest the existence of an essential correlation between STAT3 and cell metabolism; the latter process is aberrantly regulated in cancer cells." (PMID 31947710, 2020). "It has been reported that IL-10 can regulate proliferation, invasiveness, and EMT by activating STAT3 signaling in other malignant tumors." (PMID 33372604, 2020). "Pivotal mediators of cancer-induced cachexia are the transcription factors STAT3 and NF-κB, which, in turn, are mainly activated by the circulating pro-inflammatory cytokines, such as IL6 and TNFα, respectively." (PMID 32824440, 2020). "Janus kinase (JAK)/ signal transducer and activator of transcription 3 (Stat3) pathway plays significant roles in cancer progression, migration, apoptosis and immunity." (PMID 32691369, 2020). "The intrinsic generation of ROS, a by-product of mitochondrial respiration, is regulated by STAT3; high ROS levels greatly affect cancers and STAT3 addiction." (PMID 32331320, 2020). "Taken together, the results showed that FOXD2-AS1 was involved in cancer stemness maintenance and chemoresistance promotion in a manner that is strongly dependent on STAT3." (PMID 31959918, 2020). "By inhibition of STAT3, resveratrol stimulates apoptosis and autophagy in cancer cells to reduce their progression." (PMID 32163546, 2020). "In cancer cells, the endogenous inhibitors of the STAT3 signaling pathway undergo downregulation, which mediates the enhanced proliferation and malignancy of cancer cells." (PMID 32545648, 2020). "While, STAT3 pathway is another crucial player involves in the maintenance, growth and viability of cancer stem cells." (PMID 32887217, 2020). "STAT3 signaling is tightly involved in cancer development including cancer initiation, cancer progression and drug resistance." (PMID 32657763, 2020). "The IL-6/JAK2/STAT3 signaling pathway is currently the central object of research on cancer cachexia." (PMID 33158194, 2020). "Focusing on pantoprazole, we show that it significantly reduced human cancer cell proliferation by inhibiting cellular H+ extrusion, increasing K+ conductance and promoting cyclin D1-dependent cell cycle arrest and preventing STAT3 activation." (PMID 32164284, 2020).
cancer (continued). "The signal transducer and activator of transcription 3 (STAT-3) is an antiapoptotic protein playing an important role in cancer cell proliferation, invasion, and migration." (PMID 33256185, 2020). "In an experiment on breast cancer, MSCs were demonstrated to suppress cancer cell growth and sensitize the cancer cells to radiotherapy through inhibiting the STAT3 signaling pathway." (PMID 33163402, 2020). "As the downstream signaling module of many cytokines and soluble factors, Signal Transducer and Activator of Transcription-3 (STAT3) appears to be an important regulator of Treg cell accumulation and function in cancer." (PMID 33143070, 2020). "It was also reported that activated STAT3 is a critical downstream effector of Src kinanse-induced oncogenic signaling in human cancer cells." (PMID 31929760, 2020). "STAT3 activation in CD8+ cytotoxic T cells was responsible for the immune evasion in cancer patients." (PMID 31913856, 2020). "Recent studies have found that chronic infection or inflammation mediated by NF-κB and STAT3 plays a pivotal role in linking inflammation and cancer." (PMID 33182552, 2020). "With a large number of human cancers, both EBV-related and unrelated, demonstrating constitutively active STAT3, the predictive STAT3-gene signature also opens the possibility of personalizing synthetic lethal therapy for patients with such STAT3hi cancers." (PMID 33002095, 2020). "Upregulated STAT3 contributes to tumorigenesis by increasing cancer proliferation, metastasis, drug resistance, and prevents apoptosis." (PMID 33028364, 2020). "A combination of immunotherapy and small molecule inhibitors was an effective choice and targeting STAT3 directly or indirectly was also the potential approach for cancer therapy." (PMID 32486001, 2020). "STAT3 can regulate the growth cycle of cancer cells by affecting the expression of cyclin D1 and P27." (PMID 32382281, 2020). "Search for gene targets among cancer-related pathways revealed the transcription factor STAT3 as a potential target." (PMID 33180876, 2020). "As previously explained, aberrant STAT3 activity drives the expression of genes that promote the cancer phenotype, including proliferation, resistance to apoptosis, metabolic changes, metastasis/angiogenesis, and immune system derangement." (PMID 33003453, 2020). "In patients with cancer, IL-6 binds to its receptor IL-6R and exerts its effect by activating the signal transducer and activator of transcription 3 (STAT3)." (PMID 32230855, 2020). "It is activated indefatigably in cancer cells as compared to normal cells, provoking new approaches to inhibit STAT3 activation for the suppression of tumor growth." (PMID 33013353, 2020). "It is responsible for BC progression and increased stemness properties, which are primarily mediated by TLR-4 leading to the induction of NF-κB and STAT3 pathways, two important pathways in cancer progression." (PMID 32796696, 2020). "The in vivo efficacy of the VEGF–4-1BB system has been tested in high-grade glioma murine models overexpressing PDGFRβ and STAT3 in cancer precursor cells of newborn mice." (PMID 32957732, 2020). "Inhibition of STAT3 signaling plays a critical role in RES‐induced suppression of several cancer types." (PMID 33040485, 2020). "Given the role of the Stat3 pathway in cancer development, this news is disappointing for anticancer treatment." (PMID 31920463, 2020). "In GC cells, the STAT3 signaling pathway increases the invasion and migration of cancer cells via the stimulation of MMP-13." (PMID 32545648, 2020). "Although it was reported that there is crosstalk between STAT3 and NF-κB in regulating the inflammatory pathway and cancer development, the outcomes of this crosstalk are contradictory." (PMID 31511651, 2020).
cancer (continued). "The central role of STAT3 in the transformation of many cancers has elevated this transcription factor to a protein with oncogenic features." (PMID 33374980, 2020). "Strikingly, STAT3 depletion-induced miR-34a upregulation was abrogated by further leptin stimulation in cancer cells, implying that miR-34a is a signaling factor mediating the indirect effect of STAT3 on PAI-1 downstream of leptin/OBR." (PMID 33371368, 2020). "Because the activation of STAT3 occurs in both cancer and stromal cells, it allows for crosstalk of STAT3 signals." (PMID 32331320, 2020). "Inhibited growth and induction of apoptosis through inactivation of JAK2/STAT3 signaling in many cancer cells and tumors have been demonstrated in many published studies." (PMID 33123268, 2020). "As a transcription factor, STAT3 has been reported to promote the expression of cancer-promoting molecules such as Bcl-2, Survivin, and c-Myc." (PMID 32943090, 2020). "STAT3 is able to promote the proliferation and invasion of cancer cells and induces chemoresistance." (PMID 32545648, 2020). "As it was mentioned previously, STAT3 drew major attention recently because it is constitutively expressed in several cancers." (PMID 36046384, 2020). "These molecules, including pro-inflammatory cytokines, have the potential to induce lysis in cancer cells through STAT3 inhibition." (PMID 32204484, 2020). "Although research is undergoing to improve the formulations of phytochemical compounds for better therapeutic outcomes, the use of phytochemicals as natural inhibitors of STAT3 has shown promise in various cancer cell lines and models." (PMID 32731620, 2020). "Curcumin, a polyphenol derived from turmeric, has been shown to inhibit STAT3 signaling in multiple cancers." (PMID 30959799, 2019). "STAT3 was identified in the intersection candidate of MPC1 interacting protein set with the KEGG pathway in cancer gene set from GSEA." (PMID 30770798, 2019). "ROS generation, DNA damage, cell cycle, expression of TLR9, AIM2, NF-kB, STAT3, and RNA for 44 genes affecting the cancer cell viability were evaluated." (PMID 31205871, 2019). "Proliferative endothelial cells are able to release factors to induce cancer cell migration with the activation of pro-migratory signals, such as STAT3." (PMID 30947697, 2019). "Accumulating evidence has revealed that STAT3 and NF-κB are involved in a variety of biological processes, such as inflammation, and cancer progression and growth." (PMID 31248140, 2019). "This study suggested a solid preclinical proof-of-concept for APTSTAT3 as a powerful agent for STAT3 inhibition for targeting broad array of cancers with constitutively activated STAT3." (PMID 31140150, 2019). "The fact that the substantial loss of p-STAT3 is seen under conditions affecting only IL-6/IL-6R signaling suggests that the contribution of IL-11/IL-11R to maintaining constitutive p-STAT3 levels in these cancer cells is relatively small." (PMID 31491838, 2019). "The oncogenic transcription factor signal transducer and activator of transcription 3 (STAT3) is overactive in most of human cancers including CRC." (PMID 31287013, 2019). "The enhanced expression of STAT3 is manifested in ER-negative breast cancers and closely related to the invasiveness and metastasis of cancer cells." (PMID 31252615, 2019). "One of the novel strategies to prevent sustained STAT3 over-expression in cancer cells is through the activation of intrinsic regulators such as SHP-1." (PMID 31619257, 2019).